RNU6-1188P (RNA, U6 small nuclear 1188, pseudogene)
Gene: Small nuclear RNA gene on chromosome 12 (116,082,570 to 116,082,676, forward strand). Ensembl gene ENSG00000200665.
Homologues: Orthologues: chimpanzee U6 (99% identical), macaque U6 (96% identical), mouse Gm24035 (84% identical), dog U6 (79% identical), rat U6 (78% identical), dog U6 (74% identical), mouse Gm24892 (74% identical), pig U6 (73% identical). Paralogues in human: RNU6-698P (86% identical), RNU6-891P (86% identical), RNU6-38P (85% identical), RNU6-468P (85% identical), RNU6-1145P (84% identical), RNU6-116P (84% identical), RNU6-25P (84% identical), RNU6-310P (84% identical), RNU6-33P (84% identical), RNU6-40P (84% identical), RNU6-41P (84% identical), RNU6-47P (84% identical), and 1283 more.